STAT3 (signal transducer and activator of transcription 3)
Diseases named in the same sentence as STAT3 in open-access papers (continued):
Sharing a sentence is not in itself a finding about the gene and the disease.
tumor (continued). "Previous studies have shown that abnormal STAT3 activation promotes the recruitment immune cells and impairs their function, resulting in immune escape of tumor cells." (PMID 37724127, 2023). "In B16 and RENCA mouse models, STAT3 signaling is considered a fundamental factor in increasing angiogenesis activity in tumor cells." (PMID 37875976, 2023). "On the other hand, activation of STAT3 signaling pathway promoted tumor progression and angiogenesis through the upregulation of VEGFA expression." (PMID 36720310, 2023). "The signal transducer and activator of transcription 3 (STAT3) is a transcription factor that acts as a novel target for tumor therapy." (PMID 37765192, 2023). "Mechanistically, TCAF2 inhibits the expression and activity of TRPM8, leading to Wnt5a secretion in TPCs, which facilitates EMT via the activation of the STAT3 signaling pathway in tumor cells." (PMID 37635201, 2023). "With 2.5 × 106 STAT3–/– T cells added to the graft, the ALL cells were eliminated in approximately 50% of recipients, but all the recipients given 1.0 × 106 STAT3–/– T cells had progressive tumor growth." (PMID 37526084, 2023). "These transcription factors, in turn, exert influence on many intracellular signaling pathways, including the Wnt/TCF4 and STAT3 pathway, thereby contributing to tumor initiation and progression in response to treatments." (PMID 37784157, 2023). "The results showed that astaxanthin and si-STAT3 both suppressed the growth of tumors, with tumor volume reduction rates of 54% and 75%, respectively." (PMID 38031104, 2023). "SD-36 effectively degraded STAT3 protein in both xenograft tumor tissue and normal mouse tissue, leading to complete and durable tumor regression in a xenograft tumor model at well-tolerated doses." (PMID 37669923, 2023). "In further development, the Wnt signaling pathway, IL-6/STAT3 signaling pathway, changes in tumor immune microenvironment, and epithelial-mesenchymal transformation play an important role in the malignant transformation process of tissues." (PMID 38098990, 2023). "The synergistic effect of dasatinib on gemcitabine did not only decrease the Src level but also STAT3, ERK, and p-AKT, which are tumor-associated pathways." (PMID 36975494, 2023). "Previous studies have shown the potential of STAT3 inhibitors in combination with EGFR-TKIs for anti-tumor therapy." (PMID 37649478, 2023). "For instance, glioblastoma stem cell-derived exosomes skewed monocytes to pro-tumor M2 macrophage by transferring them with STAT3, the activation of which we have already seen to induce the pro-tumor TAMs." (PMID 38035101, 2023). "STAT3 directly interacts with the NF-kB and ReLA in tumor trapping in the nucleus and contributes to the activation of NF-kB in cancer." (PMID 37298889, 2023). "STAT3 inhibitor (stattic) reversed PDL1/2 induction but maintained IFNγ-mediated anti-tumor responsiveness, underscoring that immune evasion can be alleviated." (PMID 37686465, 2023). "NLK directly interacted with STAT3 and decreased the CCL2 expression, inhibiting the recruitment of tumor-associated macrophages (TAMs) in the TME." (PMID 38008713, 2023). "The pivotal role of STAT3 in tumor development stems from its capacity to regulate the transcription of genes involved in various key processes, such as the cell cycle (CCND1, CCNE1), metabolism (OCT1, HIF1A), and cell survival (BCL2, BCLXL, and HSP70)." (PMID 37474926, 2023). "This corroborates data from PDAC models, which have shown that inhibition of downstream KRAS signalling member MEK combined with STAT3 resulted in stromal remodelling and induced anti‐tumour immune responses." (PMID 37199043, 2023). "Functional studies have shown that PFA1 tumor cells reprogram myeloid cells to a myeloid-derived suppressor cell (MDSC)-like phenotype through an NF-κB/IL-6/STAT3 signaling pathway." (PMID 37694144, 2023).
tumor (continued). "In mice, the systemic delivery of STAT3/EKEVs suppressed tumor xenografts via STAT3-induced apoptosis, combating the EGFR resistance." (PMID 37754880, 2023). "While persistent STAT3 activation in muscle cells results in wasting, STAT3 hyperactivation is a feature of many tumor cell types." (PMID 36672227, 2023). "Other studies have shown IL6 polarizes M2 macrophage in CRC39 and that IL6/STAT3 can form a positive feedback loop to stimulate tumor growth and progression." (PMID 37749297, 2023). "Stat3 signaling pathway is crucial for MDSC population expansion, and the activity of Stat3 increases in MDSCs during tumor-bearing conditions." (PMID 34976216, 2022). "Over-activation of STAT3 can promote tumor growth either directly through tumor autonomic mechanisms or indirectly by modulating antitumor responses of tumor-associated stroma and immune system." (PMID 36591515, 2022). "Secreted factors in the TME interact with and recruit immune cells, where STAT3 signaling also plays crucial roles in generating tumor-promoting inflammation and immunosuppression." (PMID 35406557, 2022). "Signal transducer and activator of transcription 3 (STAT3) is a crucial molecule for tumor cell proliferation and survival." (PMID 35936759, 2022). "In penile cancer, enforced expression of CXCL13 stimulates tumor metastasis by inducing the expression of metastasis-related MMP2/MMP9 through STAT3 and ERK1/2 signaling pathways." (PMID 36612163, 2022). "STAT3 plays a dual role in tumor inflammation and immunity by promoting the pro-tumor inflammatory pathway of nuclear factor-κb (NF-κb) and interleukin-6 (IL-6)-GP130-Janus kinase (JAK) and by inhibiting STAT1 and NF-κb-mediated Th1 antitumor immune responses." (PMID 36686662, 2022). "By transfecting tumor cells with dominant-negative STAT3, the authors showed that blocking STAT3 signaling leads to apoptosis." (PMID 35270020, 2022). "Very little is known about the role of the JAK/STAT3 pathway in human SHH MB tumor progression and drug resistance." (PMID 35835937, 2022). "Tumor-derived angiogenic factors were regulated by various signaling pathways, such as STAT3, ERK, AKT, and NF-κB pathways." (PMID 35053547, 2022). "It has been shown that elevated STAT3 expression and enhanced phosphorylation in tumour cells of PCNSL can suppress the immune response of tumour cells." (PMID 36061189, 2022). "FABP4 upregulation leads to the activation of the IL-6–STAT3–ALDH1 signalling pathway and an increase in levels of STAT3-activating cytokines, which enhances the stemness of tumour." (PMID 35899119, 2022). "TAMs secrete cytokines (IL6, IL10, etc.)and exosomes (miR-21-5p, miR-155-5p, etc.)through NFKB1 signaling pathway, STAT3 signaling pathway, and other pathways to act on tumor cells and immune cells, regulating the process of CRC." (PMID 35186730, 2022). "Physically, STAT3 interacts with NF in tumor and tumor-associated immune cells, wherein lactoglobule-EGF Factor 8 (MGF-E8)/STAT3, Sonic Hedgehog/EGFR/STAT3/Sox2 pathways, and CSC-like phenotypes were promoted by tumor-associated macrophages." (PMID 36061200, 2022). "IL-6 is known to lead to the activation of STAT3, which is a proto-oncogene that can induce tumor formation." (PMID 35205671, 2022). "Immunohistochemical analysis of tumor tissues showed that p-STAT3, Bcl-2, and survivin were changed accordingly." (PMID 35710492, 2022). "In RB, high expression of LINC00324 competitively inhibits miR-769-5p, upregulates the expression of STAT3, and then activates the Jak/STAT3 signaling pathway to promote tumor progression." (PMID 36620587, 2022). "Using a conditional KO mouse model with ID2 overexpression in DCs, the authors corroborated that STAT3 deficiency and expression of ID2 in DCs enhanced the anti-tumor response." (PMID 35806328, 2022). "It is interesting to note that STAT-3 inhibition by PN has also been correlated not only with apoptosis induction in tumor cells but also with reversed drug-resistance." (PMID 35203723, 2022).
tumor (continued). "Arnicolide D, a sesquiterpene lactone isolated from Centipeda minima, has recently been shown to exert anti-tumor activity against triple-negative breast cancer cells by inhibiting the activation of Akt/mTOR and STAT3 signaling pathways." (PMID 36428613, 2022). "Constitutive activation of STAT3 can effectively induce malignant transformation and tumor metastasis in ESCC." (PMID 35614034, 2022). "Considering STAT3 contributes to both tumor growth and the promotion of tolerogenic immune cells, it is an ideal target for cancer therapy development." (PMID 36031601, 2022). "Immunohistochemical analysis of tumor tissues demonstrated that, compared to the NC group, p-STAT3, cyclin D1, and c-myc were enhanced in the Abx group but were decreased in the Abx+Stattic group." (PMID 35710492, 2022). "In a loop of cytokine signalling, IL-6 from SCs through the STAT3 pathway triggered tumour cell EMT and migration, while tumour-derived IL-1β activated the NF-kappa B pathway in glia and further induced SC cytokine secretion from SCs." (PMID 35269454, 2022). "Many studies have reported that STAT3 transcriptionally regulates numerous downstream target genes that are crucial for tumor cell growth, migration, invasion, and immune evasion." (PMID 34992215, 2022). "Exosomal miR-106b found in colorectal cancer also suppresses PDCD4 driving both IL-6/STAT3 and mTOR signalling to promoting regulatory polarization in tumor macrophages." (PMID 35320943, 2022). "We also evaluated the activation status of transcription factors NF-κB and STAT3, potent activators of inflammatory pathways that contribute to oncogenic signaling leading to enhanced cell proliferation and tumor growth." (PMID 35387985, 2022). "While the inhibition of JAK has yielded contradicting results, the selective inhibition of STAT3 is more promising as this targets both tumor intrinsic pathway signaling as well as STAT3 inhibition within the immune cells." (PMID 35372020, 2022). "In most cancer cells, STAT3 is phosphorylated as a result of either increased oncogenic signals or decreased tumor-suppressive pathways." (PMID 36496998, 2022). "Most notably, there has been minimal focus on the studies that shed light on how Stat3 inhibitors alter the dynamics of Stat3 processing in tumor cells." (PMID 35276290, 2022). "Studies in animal models of spontaneous gastrointestinal cancer with hyperactive gp130 signaling, mediated via IL-11, show that Bazedoxifene treatment suppressed tumor growth via STAT3 mechanisms." (PMID 35053592, 2022). "To address the role of LCN2 in the collaboration between STAT3 and NF-kB activated by IL-6, we analyzed the expression of the STAT3-mediated PI3K signaling pathway and NF-kB/STAT3 target genes related to survival, anti-apoptosis, and tumor progression." (PMID 35470375, 2022). "The role of S1PR1 in tumour formation is consistent with the finding of S1PR1 upregulation in STAT3-positive tumours and in oestrogen receptor-positive breast cancer cells." (PMID 35563301, 2022). "An in-vivo study reveals that curcumin injected with tumorspheres of lung cancer NCI-H460 cells in nude mice suppressed the tumor growth via repressing the JAK2/STAT3 signaling pathway." (PMID 35883653, 2022). "Both NFκB-driven and exosomal miR-21a was shown to silence PDCD4, a tumor suppressor and IL-6 inhibitor, promoting the expansion of MDSCs in a IL-6/STAT3 dependant manner in lung cancer." (PMID 35320943, 2022). "By inhibiting STAT3 phosphorylation and p-STAT3-mediated DNA transcription and replication, it can promote tumor cell apoptosis." (PMID 35463085, 2022). "These neurohormones activate inflammatory mediators such as IL-1, TNF-α, and IL-6, which additionally activate nuclear factor kappa B (NF-ĸB) and signal transducer and activator of transcription 3 (STAT-3)—transcription factors involved in tumor progression." (PMID 36078233, 2022).
tumor (continued). "Previous studies have demonstrated that IL6-mediated dysregulation of JAK/STAT3 pathway significantly correlates with proliferation, metastasis and survival of tumor cells." (PMID 36032140, 2022). "As expected, Western blot analysis of the tumor tissues showed that LLL12B suppressed the phosphorylation of STAT3 (Y705) and cyclin D1 expression." (PMID 36009550, 2022). "On the contrary, survivin can be acetylated by CREB binding protein (CBP) at K129 to promote its nuclear localization and act as a tumor suppressor by inhibiting the transactivation of signal transducer and activator of transcription 3 (STAT3)." (PMID 35216622, 2022). "Results in vitro showed that PD-L1 expression in the tumor was enhanced by IL-6 via the JAK1/Stat3 pathway, which induced immune evasion." (PMID 35550592, 2022). "IL-17-mediated tumor angiogenesis is involved in the activation of the Stat3/GIV signaling pathway and subsequent upregulation of vascular endothelial growth factor production in NSCLC cells." (PMID 36035842, 2022). "STAT3 appears to be necessary for regulatory B (Breg) cells, a B cell counterpart to Tregs that produces anti-inflammatory IL-10 and is pro-tumor." (PMID 35406557, 2022). "No significantly correlation was found between the expression of p-STAT3 and gender, age, or tumor differentiation." (PMID 36225196, 2022). "Researchers recently demonstrated that tumor-infiltrating M-MDSCs downregulates the STAT3 activity through hypoxia-induced activation of CD45 phosphatase that favors their rapid differentiation into TAMs." (PMID 35183252, 2022). "Collectively, these data suggest that Siglec-15 promotes tumor progression and the activation of STAT1/STAT3 signaling pathway, which is associated with tumor immunity." (PMID 35769818, 2022). "Enhanced fatty acid oxidation through STAT3 signaling activation protects Tc9 cells from tumor- or TME-induced lipid peroxidation and ferroptosis." (PMID 35192544, 2022). "A runaway tumor growth was inhibited by restricting STAT3 activation, as well as by activation of the intrinsic apoptotic pathway." (PMID 36171605, 2022). "In contrast, we show that STAT3 signaling in tumor cells treated with EVsMMA-MRC5 promotes TGF-β signaling in a positive crosstalk interaction to drive EMT." (PMID 36266345, 2022). "These SIE-directed programs give STAT3 signaling a decidedly pro-survival, pro-tumor flavor, which is advantageous in the setting of KM-LUAD." (PMID 35406557, 2022). "R-PTP-κ is a tumor suppressor that dephosphorylates and inactivates oncogenic proteins such as STAT3, EGFR and CD133." (PMID 36551956, 2022). "Transcriptomics + Proteomics + Metabolomics:High STAT3 expression → OXPHOS downregulated (Transcriptomics).High STAT3 expression → TCA cycle/OXPHOS downregulated (Proteomics).High PDK4 expression → inhibited PCa tumor growth." (PMID 35736421, 2022). "Hyperactivation of Stat3 is present in a large number of cancers and has been reported to be required for tumor cell growth and survival, as well as angiogenesis, metastasis, and immune evasion." (PMID 35411090, 2022). "Tumor-derived factors induce the constitutive activation of JAK/STAT3 and prevent the differentiation of immature myeloid cells into mature dendritic cells, resulting in a decreased number of mature DCs." (PMID 35326392, 2022). "The majority of STAT3-dependent effects in the tumor microenvironment are described in the context of T cells, macrophages or dendritic cells that have been extensively reviewed by others." (PMID 35865518, 2022). "Recent studies have shown that formononetin can inhibit PD-L1 expression by interfering with the interaction between MYC and STAT3, while enhancing the activity of CTLs and restoring their ability to kill tumor cells." (PMID 35463082, 2022). "STAT3 is proposed to function as an oncogene in a variety of malignant tumors and participate in signal transduction in tumor stem cells." (PMID 35093120, 2022).
tumor (continued). "This feedback is often dysregulated in tumor epithelial cells and the immune architecture of the tumor microenvironment, leading to excessive STAT3 signaling during tumor development and progression." (PMID 35053592, 2022). "Taken together, these mechanistic experiments demonstrate RELA and STAT3 as required for cytokine and tumor microenvironment signaling to PDZK1IP1 induction." (PMID 36253360, 2022). "To evaluate the clinical significance of LMO2 and STAT3 signaling, we performed pan-cancer survival analysis with LMO2- & STAT3-signature in 14 tumor types from TCGA." (PMID 35805116, 2022). "Together, these findings emphasize the importance of IL-6 and STAT3 in multiple tumor-suppressive functions of TRAF3." (PMID 36291813, 2022). "The inflammatory-related transcription factor, STAT-3, is hyper-activated in several human cancers, leading to proliferation, apoptosis, division, and differentiation of tumor cells." (PMID 36432658, 2022). "In the tumor and its microenvironment, STAT1 and STAT3 have both been shown to be expressed by tumor cells and infiltrating immune cells and to be involved in regulating cancer adaptive immunity." (PMID 35267462, 2022). "STAT3 also plays a critical role, not only in signal transduction, but also through cancer-promoting inflammation and increasing anti-tumor immunity." (PMID 36672573, 2022). "Further experiments indicated that STAT1 and STAT3 contributed to tumor abrogation by Siglec-15 RNAi." (PMID 35769818, 2022). "Our results indicate that the combination of Stt + Tcz effectively and synergistically inhibits the IL-6/IL6R/STAT-3 pathway in tumor cells." (PMID 35465350, 2022). "Signal transducer and activator of transcription 3 (STAT3) mediates tumor-induced immunosuppression at many levels." (PMID 34875483, 2022). "Accordingly, use of ruxolitinib or depletion of STAT3 led to regression of tumor growth in vivo, suggesting that IL-6 or possibility other inducers of JAK:STAT signaling are clearly at play during in vivo acquisition of drug resistance." (PMID 35729402, 2022). "Abnormal hyperactivation of signal transducer and activator of transcription-3 (STAT3) in tumor-infiltrating immune cells positively regulates the number of Tregs and MDSCs." (PMID 36532066, 2022). "CSC acts on TAM surface receptors by secreting chemokines and TGF-β, and activates STAT3 and NF-kB, leading to the immune escape of tumor cells." (PMID 36686745, 2022). "Knockdown of STAT3 using siRNA successfully inhibits tumor growth with increased tumor infiltration of CD8+ T cell and NKT cell in murine melanoma models." (PMID 36003395, 2022). "We were thus able to evaluate changes in the epithelium as well as the tumor microenvironment over the course of de novo tumor formation and progression in response to the conditional knockout of STAT3 in CAFs." (PMID 35803738, 2022). "Only the use of DC stimulated with LMM3 lysate prepared with inactivated STAT3 produced some anti-tumor effect although lower than that attained with ICI in both subcutaneous tumors and lung metastases." (PMID 35922755, 2022). "The ratio of p-STAT3/STAT3 protein expression in tumor tissue was considerably lower in the VV-IL-37-GFP group than in the VV-mock-GFP group." (PMID 36146619, 2022). "Except for tumor growth inhibition, monotherapies of STAT3 small-molecule inhibitors are found to decrease immunosuppressive macrophages and Tregs, increase cytolytic CD8+ T-cells and elevate the secretion of proinflammatory cytokines and chemokines." (PMID 36080223, 2022). "Taken together, our study uncovered the key role of the RSL1D1/RAN/STAT3 regulatory axis in autophagy and tumor progression in CRC, providing a new candidate target for CRC treatment." (PMID 35013134, 2022). "This combination treatment showed a significant suppression of an angiogenesis and anti-apoptosis effect in tumor cells with the downregulation of STAT3 Bcl-2 families and VEGFR mRNA." (PMID 35158821, 2022).